Y_RNA (Y RNA )
Gene: Miscellaneous RNA gene on chromosome 4 (121,329,069 to 121,329,170, reverse strand). Ensembl gene ENSG00000207148.
Homologues: Orthologues: chimpanzee Y_RNA (98% identical), macaque Y_RNA (92% identical). Paralogues in human: Y_RNA (90% identical), RNY3 (89% identical), Y_RNA (89% identical), Y_RNA (88% identical), Y_RNA (87% identical), RNY3P1 (86% identical), RNY3P16 (86% identical), Y_RNA (86% identical), RNY3P14 (85% identical), Y_RNA (85% identical), Y_RNA (84% identical), RNY3P13 (83% identical), and 95 more.